TYMP (thymidine phosphorylase)
Diseases named in the same sentence as TYMP in open-access papers (continued):
Sharing a sentence is not in itself a finding about the gene and the disease.
tumor (continued). "TAS102 treatment effectively reduced tumour burden and metastasis, particularly in TYMP-overexpressing ID8Luc mice, as evidenced by lower luciferin intensity and Ki67 staining." (PMID 39548315, 2025). "Targeting TYMP has emerged as a promising strategy for cancer therapy, and TYMP-activated anti-tumor drugs represent an important therapeutic approach." (PMID 40303404, 2025). "Beyond its physiological roles, TYMP contributes significantly to tumor growth and cancer progression, where it promotes angiogenesis, modulates epigenetic genes, inhibits apoptosis, and acts as a critical enzyme in the nucleoside metabolic rescue pathway." (PMID 40303404, 2025). "Although TYMP exerts several promoting effects on tumor cell growth and development, it also holds therapeutic potential in cancer treatment." (PMID 40303404, 2025). "The final step occurs predominantly in tumor tissues, where thymidine phosphorylase (TP) converts 5′-DFUR into 5-FU, enhancing antitumor effects while minimizing systemic toxicity due to low TP activity in normal tissues." (PMID 40722718, 2025). "Because of differential expression of thymidine phosphorylase, the active metabolite of capecitabine is thought to localize more readily to tumor cells, reaching local tumor concentrations that are approximately 3-fold higher than in healthy tissue." (PMID 38297307, 2024). "It then undergoes further metabolism by thymidine phosphorylase at the tumor site to create the active metabolite 5-fluorouracil." (PMID 38297307, 2024). "Capecitabine is an oral prodrug that is converted to its active form 5-fluorouracil in tumor tissues, mainly through the enzyme thymidine phosphorylase (TP)." (PMID 38070191, 2024). "TYMP catalyzes reversible thymidine phosphorylation and is suggested to have a critical effect on angiogenesis, tumor growth, migration, and invasion." (PMID 39185422, 2024). "HPRT1 plays an important role in the recycling of nutrient-scarce purines in the hypoxic TME, while the role of TYMP in pyrimidine metabolism and angiogenesis suggests its contribution to tumour proliferation." (PMID 39457550, 2024). "The enzyme thymidine phosphorylase, expressed in many tumor cells, then hydrolyzes the 5-fluorouridine derivative to the active drug 5-FU." (PMID 38554983, 2024). "At the location of the tumor, capecitabine can be converted into 5-fluorouracil through the tumor-related vascular factor (thymidine phosphorylase), thereby minimizing the damage to normal cells." (PMID 37408581, 2023). "5-FU is administered intravenously (IV) as a rapid continuous bolus infusion with leucovorin (LV) or as the oral prodrug capecitabine, which is converted into 5-FU by the thymidine phosphorylase (TP) in tumor sites." (PMID 37233460, 2023). "Comparing micro- and macrodissected tumor tissues, the highest TYMP gene expression was found in macrodissected tissues, including both stromal and epithelial cells." (PMID 35567733, 2022). "It was also reported that tumor-bearing animals had elevated thymidine phosphorylase activity in their ascites and plasma." (PMID 36430649, 2022). "DT-enhanced survival, CRT expression, and apoptosis of tumor cells (TUNEL+) were clearly separated from TYMP expression and CD31+ cells in the PCA space and were associated with tumor growth, whereas TPI and IMQDCs largely overlapped." (PMID 36090972, 2022). "The mean TYMP gene expression in macrodissected tumor tissues (macTYMP), microdissected tumor epithelial cells (tecTYMP), and microdissected tumor stroma (stromaTYMP) was 0.52 ± 0.56, 0.24 ± 0.23, and 0.32 ± 0.36, respectively." (PMID 35567733, 2022). "Clinical findings have shown that TYMP is a marker that reflects the characteristics of the tumor stroma and is closely related to poor prognosis in various cancers." (PMID 35314790, 2022). "Collectively, these data show that CD8+ T cells coexpressing PD1 and TYMP preferentially accumulated in the tumor." (PMID 36090972, 2022).
tumor (continued). "The fact that the last conversion is assisted by thymidine phosphorylase—the concentration of which is considerably higher in the tumour compared to healthy tissue—grants tumour selectivity during treatment." (PMID 36567978, 2022). "FTD/TPI is an anti-tumor medication administered orally that consists of trifluridine (a nucleoside analogue), and tipiracil (a thymidine phosphorylase inhibitor), and is registered for mCRC refractory to standard regimens in over 93 countries." (PMID 36313317, 2022). "Lastly, the 5-deoxy-5-fluorouridine is converted within the tumor cells into 5FU via thymidine phosphorylase." (PMID 35698681, 2022). "TYMP promotes angiogenesis, escapes apoptosis, and stimulates tumour growth, and the accumulation of high levels of macrophages is positively correlated with high NLR levels." (PMID 34997351, 2022). "TYMP has several tumor-promoting functions and is positively correlated with angiogenic factors such as vascular endothelial growth factor (VEGF) and microvessel density." (PMID 36090972, 2022). "It was previously demonstrated that both tumor cells and the surrounding matrix cells expressed TYMP in the TME." (PMID 35250999, 2022). "It is highly selective for cancer cells and is converted into 5-fluorouracil with antitumor activity by thymidine phosphorylase in tumor tissue, to play an anti-tumor effect." (PMID 36278891, 2022). "One of the potential advantages of this mechanism for increasing tumor cytotoxicity is that thymidine phosphorylase is overexpressed in tumor tissues." (PMID 36142122, 2022). "Apparently, the effect of tumor suppression is obviously related to the antiangiogenesis ability of TYMP inhibitor." (PMID 35314790, 2022). "Although some studies evaluating TYMP as a predictive marker for chemotherapy have shown comparable results between microdissected tumor epithelial cells and macrodissected tissues, other studies show contradicting results." (PMID 35567733, 2022). "In the study, it was possible to identify TAM both in micro- and macrodissected tissue by including the macrophage-specific marker CD163, and further, to stratify the influence of TAM in the tumor microenvironment and its correlation to TYMP expression." (PMID 35567733, 2022). "CAP is an alternative drug to 5-F uracil (5-FU) that acts in tumor tissue catalyzed by thymidine phosphorylase to 5-FU." (PMID 35356252, 2022). "Thymidine phosphorylase (TP) is identified in higher amounts at the tumor level; thus the conversion of capecitabine to 5-fluorouracil occurs mainly at the tumor level, resulting in a low concentration of the agent in plasma or normal tissues." (PMID 36233450, 2022). "This means that tumours with the highest expression of TYMP and TK1, which would result in high FdUMP levels, also had high ABCC5 expression, which would result in efflux of FdUMP." (PMID 34132895, 2021). "Consistent with this idea, upon grouping the DepMap cancer cell lines according to tissue origin, we noted that CDKN2A status and TYMP expression have varying effects on controlling TYMS dependency in different tumor types." (PMID 34454516, 2021). "Other factors such as TGF-β, TNF, WNT7B, and thymidine phosphorylase promote tumor progression by recruiting and activating endothelial or other cells (such as fibroblasts) that further support angiogenesis in the tumor microenvironment." (PMID 34178692, 2021). "TYMP is a rate-limiting enzyme in the thymine catabolic pathway and contributes to tumor angiogenesis." (PMID 32737333, 2020). "In the presence of tipiracil, the anti-tumor activity of trifluridine is augmented through inhibiting its metabolism by thymidine phosphorylase." (PMID 33120790, 2020). "Capecitabine is selectively converted from 5′-DFUR to 5-fluorouracil (5-FU) in tumours by thymidine phosphorylase (TP)." (PMID 32066801, 2020).
tumor (continued). "Capecitabine is an oral prodrug that is metabolized to 5-FU through a 3-step enzymatic process, the final step of which utilizes the enzyme thymidine phosphorylase (TP), which is preferentially expressed in some tumor tissues." (PMID 32426292, 2020). "Indeed, even though the loss of TYMP expression leads to an unsuccessful 5FU conversion, causing inevitably the treatment failure and severe cytotoxic effects due to its accumulation, its expression was found to be significantly higher in GC tumor tissues, creating a paradox." (PMID 32887417, 2020). "Capecitabine is finally converted to fluorouracil by thymidine phosphorylase, which is expressed at higher levels in tumor tissue, leading to the accumulation of fluorouracil in tumor tissue." (PMID 29488121, 2018). "The final process of capecitabine is converted to 5-FU through the enzymatic activity of thymidine phosphorylase (TP), which is known to be over expressed in tumor cells." (PMID 29113420, 2017). "Capecitabine is an oral fluoropyrimidine that is activated in tumor tissue via a three-step enzymatic conversion that culminates in the generation of thymidine phosphorylase." (PMID 27942930, 2017). "Many genes account for several aspects of the endothelial response, such as VEGFA, IL6 and TYMP for tumor angiogenesis, and S1PR1 for development and cell differentiation." (PMID 29088816, 2017). "In contrast, capecitabine is an oral fluoropyrimidine that is metabolized primarily in the liver and converted in tumor tissues to 5-FU by the enzyme thymidine phosphorylase, which is present in higher concentrations in tumor cells than in normal cells." (PMID 27942930, 2017). "Subsequently, 5′-DFUR is metabolized to active 5-FU by thymidine phosphorylase (TP), and higher concentration of TP is present in some tumor tissues in comparison with normal tissues." (PMID 27811367, 2016). "The combined treatment was then carried out in the tumor model with the intratumoral delivery of TYMP shRNA complex first and then intravenous injection of dT-QX or PBS." (PMID 25881156, 2015). "Clearly, TYMP shRNA plus dT-QX significantly inhibited the tumor growth as compared to those of shRNA alone after two rounds of treatment." (PMID 25881156, 2015). "Capecitabine undergoes a three-step enzymatic conversion, and the final stage is catalyzed by thymidine phosphorylase, which is significantly more active in tumor tissue compared with healthy tissue." (PMID 26497654, 2015). "Clinical relevance of high levels of TK1 and TYMP was then assessed on human HCC tumor and normal liver tissues with immunohistochemical (IHC) analysis." (PMID 25881156, 2015). "Simultaneously, TYMP also acts as a platelet derived endothelial cell growth factor in tumor angiogenesis and metastasis." (PMID 25881156, 2015). "Clinically, induced high levels of TYMP have been commonly observed in tumor tissues due to inflammatory infiltration or after radiotherapeutic treatment and chemotherapy such as paclitaxel, doxorubicin and oxaliplatin." (PMID 25881156, 2015). "The prodrug capecitabine is activated by a unique mechanism that exploits the high activity of thymidine phosphorylase in malignant tissue that generates 5-FU preferentially in tumor tissue." (PMID 26497654, 2015). "In contrast, shRNA suppression of TYMP significantly enhanced the selective of the conjugate in vitro and reduced the tumor growth in vivo." (PMID 25881156, 2015). "Western blot analysis indicated that intratumoral injection of TYMP shRNA complex in vivo significantly reduced the TYMP level in tumor tissue than those of control at 72 h post injection, confirming the effectiveness of intratumoral delivery of shRNA." (PMID 25881156, 2015). "Capecitabine is an oral fluoropyrimidine, which is metabolized primarily in the liver and converted in tumor tissues to 5-FU by the enzyme thymidine phosphorylase, which is present in higher concentrations in tumor cells than in normal cells." (PMID 24392116, 2014).
tumor (continued). "Thymidine phosphorylase is found in higher concentrations in tumor tissue than in normal tissue and is upregulated by radiation in tumor tissue, but not in normal tissue." (PMID 24428956, 2014). "In prostate, it was reported that stromal factors, such as caveolin-1 and thymidine phosphorylase were related with tumor aggressiveness." (PMID 24073251, 2013). "The final stage of conversion to fluorouracil is catalysed by thymidine phosphorylase, which is appreciably more active in tumour than in healthy tissue." (PMID 23251164, 2012). "Thymidine phosphorylase (TP) is often overexpressed in tumours and has a role in tumour aggressiveness and angiogenesis." (PMID 21386840, 2011). "Another predictor that has been suggested is tumour tissue expression level of mRNA or protein of 5-FU metabolic pathway genes, such as thymidylate synthase, orotate phosphoribosyltransferase, and thymidine phosphorylase." (PMID 21364592, 2011). "This can be ascribed to a higher 5-FU concentration in tumor cells and the induction of thymidine phosphorylase by the irradiation." (PMID 20584299, 2010). "Thymidine phosphorylase is the marker of a more aggressive and malignant tumour phenotype that has increased resistance to cytotoxic agents because of the loss of apoptotic potential." (PMID 20700125, 2010). "Capecitabine generates 5-FU preferentially at the tumor site by increasing the higher activity of the enzyme thymidine phosphorylase in tumor tissue compared with the healthy tissue." (PMID 19508705, 2009). "Because the enzyme (thymidine phosphorylase) responsible for the last conversion step is more concentrated in tumour tissue than in normal tissues, FU levels in tumour tissue are selectively increased." (PMID 19491895, 2009). "In preclinical studies, irradiation with thymidine phosphorylase was found to be upregulated in tumor tissue resulting in a supra-additive effect of capecitabine on radiotherapy." (PMID 19508705, 2009). "Capecitabine is a fluoropyrimidine carbamate designed to generate 5-flurouracil (5-FU) preferentially in tumor cells as concentration of the key enzyme thymidine phosphorylase is higher in tumor cells compared with normal tissue." (PMID 19508705, 2009). "This combination is attractive because preclinical studies of taxanes support up regulation of thymidine phosphorylase in tumor tissue, and subsequent synergistic activity with capecitabine and paclitaxel or docetaxel." (PMID 18794792, 2008). "The activation is completed by the enzyme thymidine phosphorylase (TP) converting 5'-deoxy-5-fluorouridine to 5-fluorouracil, preferentially within the tumour cell." (PMID 17640356, 2007). "Beside a known elevated expression of thymidine phosphorylase within tumour cells and white blood cells, paclitaxel and other agents have the ability to induce this enzyme in the mouse model." (PMID 17640356, 2007). "This tumour selectivity is achieved through exploiting the significantly higher activity of thymidine phosphorylase in many tumour tissues compared with healthy tissue." (PMID 16641916, 2006). "Thymidine phosphorylase (TP) is often induced in the tumour microenvironment by physiological and chemical stress where it protects cells from apoptosis and helps cell survival by stimulating nucleoside metabolism and angiogenesis." (PMID 16685274, 2006). "Capecitabine is a rationally designed, orally administered, tumor-selective fluoropyrimidine that mimics continuous infusion 5-FU, which is converted to 5-FU preferentially in tumor tissue by the enzyme thymidine phosphorylase." (PMID 16396674, 2006). "This tumour selectivity is achieved through exploiting the significantly higher activity of thymidine phosphorylase (TP) in many tumour tissues compared with healthy tissue." (PMID 16251869, 2005). "Thymidine phosphorylase scores, staining intensities, and staining patterns from both tumour cells and stromal cells were available." (PMID 15150550, 2004).
tumor (continued). "Thymidine phosphorylase upregulation was seen in 54.4% and 32.6% of patients in tumour cells and stromal cells, respectively." (PMID 15150550, 2004). "The final step of this conversion is catalysed by the enzyme thymidine phosphorylase, which is overexpressed in tumour cells, thus theoretically providing a degree of specificity for tumour over normal tissue." (PMID 15505625, 2004). "Thymidine phosphorylase upregulation by several anticancer drugs implies the importance of individualised strategies for sensitisation of tumour tissues to 5-FU and its derivatives." (PMID 15150550, 2004). "The final stage of this conversion is mediated by thymidine phosphorylase, an enzyme present at significantly increased concentrations in a wide range of tumour types, including colorectal, breast and gastric cancers, compared with normal tissue." (PMID 15026800, 2004). "This efficient penetration into the interstitium of malignant tissue is the initial necessary step before DFUR enters tumour cells, where it is converted to FU by thymidine phosphorylase." (PMID 12618890, 2003). "The highly active, oral fluoropyrimidine capecitabine (Xeloda®: F Hoffmann-La Roche, Basel, Switzerland) was rationally developed to deliver 5-FU preferentially to tumours by exploiting the high concentrations of thymidine phosphorylase in tumour tissue." (PMID 14612890, 2003). "Both taxanes did not affect the pharmacokinetics of capecitabine, although upregulation of thymidine phosphorylase has been reported in tumour xenografts after exposure to paclitaxel or docetaxel." (PMID 12618890, 2003). "Thymidine phosphorylase expression and tumour-infiltrating lymphocytes were related inversely with prostate specific antigen reactivity." (PMID 11986782, 2002). "For example, expression of VEGF is four-fold higher in superficial tumours than in invasive tumours but expression of thymidine phosphorylase is 33 times higher in invasive tumours." (PMID 11953885, 2002). "The cytokine tumour necrosis factor alpha (TNF-alpha) and the enzyme thymidine phosphorylase (TP) are two factors known to promote tumour angiogenesis." (PMID 9649140, 1998). "As previously discussed, TYMP activity can activate chemotherapy drugs, while TYMP inhibitors could mitigate its angiogenic effects, thereby indirectly impeding tumor cell growth." (PMID 40303404, 2025). "Investigating its biological functions in tumors may lead to the synthesis of TYMP inhibitors, which could prevent angiogenesis and slow tumor metastasis." (PMID 40303404, 2025). "Over time, TYMP’s essential biological roles, including promoting platelet activation, osteoclast differentiation, angiogenesis, and its involvement in tumor angiogenesis, epigenetic gene modification, apoptosis resistance, and nucleoside metabolic salvage, have been gradually unveiled." (PMID 40303404, 2025). "TYMP plays a key role in helping tumor cells resist apoptosis induced by hypoxia." (PMID 40303404, 2025). "TYMP also influences tumor progression through its role in DNA methylation regulation." (PMID 40303404, 2025). "Given its involvement in cancer progression, TYMP inhibitors may prove valuable in inhibiting tumor growth and metastasis." (PMID 40303404, 2025). "Furthermore, histological immunochemistry revealed strong staining of TYMP and the proliferation marker Ki67 in untreated tumour samples." (PMID 39548315, 2025). "Interestingly, while TYMP can drive tumor growth, certain concentrations of TYMP also enhance the cytotoxic effects of chemotherapy drugs such as 5-fluorouracil (5-FU)." (PMID 40303404, 2025).